SOX9 (SRY-box transcription factor 9)
Diseases named in the same sentence as SOX9 in open-access papers (continued):
Sharing a sentence is not in itself a finding about the gene and the disease.
osteoarthritis (74 papers, 2007 to 2026). A noninflammatory degenerative joint disease occurring chiefly in older persons, characterized by degeneration of the articular cartilage, hypertrophy of bone at the margins and changes in the synovial membrane. "The levels of SOX9 acetylation are closely linked to osteoarthritis development, as they diminish nuclear entry capability and impact transactivation of the ACAN gene." (PMID 39974732, 2025). "There is a gradual decrease in the mRNA levels of Col2a1, Acan and Sox9 and an increase in Runx2 associated with osteoarthritis." (PMID 39600948, 2024). "Our results suggest Nrf2 directly regulates SOX9 in articular cartilage, and Nrf2-loss can develop mild osteoarthritis at old age." (PMID 35204144, 2022). "The results thus identified some genes whose expression appeared to be linked to SOX9 expression in isolated chondrocytes and were also altered during cartilage degeneration in osteoarthritis." (PMID 17935617, 2007). "Both strands (-5p and -3p) of has-miR-455 target the same genes to regulate articular cartilage homeostasis, with underlying treatment value for osteoarthritis (OA), are upregulated by Sox9 (SRY-box transcription factor 9), a crucial transcription factor of cartilage differentiation and function." (PMID 35310909, 2022). "Moreover, loss of SOX9 activity and subsequent decrease in target gene expression is observed in osteoarthritis and is correlated to osteoarthritis progression." (PMID 34869253, 2021). "The SRY-box 9 gene (SOX9) is our third candidate linked to osteoarthritis." (PMID 34066823, 2021). "Similarly, sox9 serves as an essential transcriptional regulator of chondrogenesis in conjunction with expression of col10, and both are implicated with osteochondral pathogenic phenotypes including osteoarthritis." (PMID 40863930, 2025). "Therefore, an important question arising is whether activation of the ISR and its associated ectopic expression of ATF4 and its downstream targets such as Sox9 may underlie common skeletal diseases such as intervertebral disc degeneration and osteoarthritis." (PMID 30024379, 2018). "Following the subsidence of inflammation, the expression of aggrecan and SOX9 in cartilage tissue was significantly elevated, suggesting potential strategies based on logic gates for the treatment of osteoarthritis (OA)." (PMID 41293317, 2025). "Recent studies indicate that Sox9 is essential in cartilage development and the pathogenesis of osteoarthritis." (PMID 41158629, 2025). "The transcription factor SOX9 emerges as a critical player across multiple disease states, with its clinical relevance particularly evident in osteoarthritis (OA), tissue repair, and chronic inflammatory conditions." (PMID 41293317, 2025). "Conversely, in conditions like osteoarthritis and acute kidney injury, SOX9 enhances cartilage matrix synthesis, mitigates inflammation, and supports tissue repair, often by modulating macrophage activity toward an M2-polarized state." (PMID 41293317, 2025). "In a study on cartilage repair in osteoarthritis, CRISPRa/i were used to activate SOX9 and repress a transcription factor involved in the activation of tumor necrosis factor RelA." (PMID 40650152, 2025). "This interaction disrupts USP7-mediated deubiquitination and leads to SOX9 degradation in osteoarthritis." (PMID 40240356, 2025). "SOX9 provides a therapeutic benefit in inflammatory diseases and tissue repair, notably by mitigating osteoarthritis and alleviating acute kidney injury." (PMID 41293317, 2025). "Decreased SOX9 expression is considered an early marker of chondrocyte dysfunction and cartilage degradation in osteoarthritis." (PMID 40869671, 2025). "Our findings provide new insights into transcription factor dynamics and their functional relevance and offer valuable insights into the role of SOX9 in osteoarthritis pathology." (PMID 39344191, 2024).
osteoarthritis (continued). "SOX9 is reported to promote cartilage repair in osteoarthritis, whereas its role in RA still needs to be further explored." (PMID 38388473, 2024). "The SOX9 is a suppressor of metalloproteinases-induced cartilage degeneration at the early stage of human osteoarthritis." (PMID 37189729, 2023). "Further analysis of these enriched pathways in injurious hydrostatic pressure highlighted differential expression of several genes known to be involved in osteoarthritis, such as Fgf2, Ep300, Ngf, Adam9, Igfbp3, Sox9, Comp, Col6a1, Col6a2 and Col11a1." (PMID 38144567, 2023). "Circ_0000423/miRNA-27b-3p/MMP-13 axis regulates cartilage ECM synthesis in osteoarthritis, and exosome-transported circRNA_0001236 enhances chondrogenesis and inhibits cartilage degeneration via miR-3677-3p/Sox9 axis." (PMID 36980895, 2023). "Pathways negatively regulated by SOX9 included osteoarthritis, the role of osteoblasts, LXR/RXR activation, GADD45, TGF-β, and the coagulation system." (PMID 37491298, 2023). "The ATRNL1 gene, which was identified in this study, can regulate the expression of SOX9 and is significantly highly expressed in the cartilage tissues of patients with osteoarthritis." (PMID 37667381, 2023). "The expression of SOX9 increases during tumorigenesis of bone and cartilage and decreases in cases of cartilage disorders, such as osteoarthritis." (PMID 37447201, 2023). "Impaired circadian rhythm induces osteoarthritis resulting from SOX9 inhibition in articular chondrocytes, and the deletion of Bmal1 also leads to reduced SOX9." (PMID 35578353, 2022). "SOX9 and aggregate sugar have a repairing effect on the damaged proteasome function of human osteoarthritis chondrocytes." (PMID 35246197, 2022). "AGN and SOX-9 were also quantified in order to evaluate additional biomarkers with a specific role in osteoarthritis pathways." (PMID 34641024, 2021). "This is especially the case for the switch of a RUNX2+ to SOX9+ cell fate, since epigenetic regulation has likely occurred in the process of osteoarthritis." (PMID 34869253, 2021). "As the major transcription factor that dictates chondrogenesis, SOX9 level in chondrocytes is remarkably reduced in the articular cartilage of osteoarthritis patients." (PMID 34220525, 2021). "Corresponding to the biological reality of cartilage diseases, such as osteoarthritis, OA, in the AC model a switch from the SOX9+ to the RUNX2+ state is possible." (PMID 34869253, 2021). "It was reported that the expression of miR-29 family members is elevated in cartilage during osteoarthritis (OA), which was suppressed by SRY-box transcription factor 9 (SOX9) in chondrocytes." (PMID 33553139, 2020). "ADAMTS5, NOTCH1, SMAD9, and SOX9 genes, enriched in the osteoarthritis pathway, were predicted as targets of a novel miRNA (3_17250)." (PMID 32316683, 2020). "Here, we examined the effect of SOX9 acetylation on ACAN transactivation in the context of osteoarthritis." (PMID 26910618, 2016). "The aim of this study was to examine the distribution of stem cell markers (Notch-1, Stro-1 and VCAM-1) and of molecules that modulate progenitor differentiation (Notch-1 and Sox9) in normal adult human articular cartilage and in osteoarthritis (OA) cartilage." (PMID 19500336, 2009). "Lenti-miR-146a-mimic suppressed the expression of Sox9 and Col2a1 in murine articular cartilage cells, whereas Lenti-miR-146a-inhibitor counteracted this effect, suggesting potential therapeutic advantages in osteoarthritis management." (PMID 41158629, 2025). "Furthermore, the expression of SOX9 is significantly reduced in individuals with osteoarthritis, particularly in age-related cartilage degeneration, when compared to controls." (PMID 41170184, 2025).
osteoarthritis (continued). "While Fisetin decreased the expression of SOX9 in human osteoarthritis chondrocytes, combining dasatinib and quercetin increased the number of SOX9+ chondrogenic progenitor cells in an in vivo intermittent hydrostatic pressure model in the posttraumatic osteoarthritis rats." (PMID 36614288, 2023). "Importantly, overexpression of SOX9 was shown to alleviate the progression of human osteoarthritis in vitro and in vivo, which would be in line with our proposed working model." (PMID 35204144, 2022). "Sox6 and Sox9 are also important factors in cartilage homeostasis that stimulate cartilage formation, which may promote bone growth and prevent osteoarthritis." (PMID 32946669, 2020). "In this review, we explore evidence suggesting that Cytl1 may be involved in the regulation of chondrogenesis, cartilage homeostasis and osteoarthritis progression, accompanied by the modulation of Sox9 and insulin-like growth factor 1 expression." (PMID 31089746, 2019). "Very little is known about the functional changes in SOX9 activity, as osteoarthritis develops." (PMID 26910618, 2016). "If CXCR1/2 signalling supports SOX9 expression, why did we not observe spontaneous osteoarthritis in CXCR2-deficient mice?" (PMID 25135253, 2015). "SOX9 has been shown to be downregulated in osteoarthritis, and this may contribute to the pathological process by causing a reduction in the expression of ECM genes." (PMID 17935617, 2007). "Hence, upregulation of DDAH1 to inhibit ADMA levels and regulate USP7-mediated SOX9 deubiquitination could be a useful strategy for the treatment of osteoarthritis." (PMID 37359559, 2023). "In addition, several genes known to play a key role in progression of osteoarthritis (e.g., Fgf2, Ep300, Ngf, Adam9, Igfbp3, Sox9, Comp, Col6a1, Col6a2 and Col11a1) were modulated in our injurious hydrostatic pressure hip cap datasets, thereby validating this approach." (PMID 38144567, 2023). "SOX9 could regulate ADAMTSs-induced cartilage degeneration in human osteoarthritis." (PMID 36242088, 2022). "Alteration of the osteoarthritis pathway due to RARγ agonist treatment was associated with the up-regulation of catabolic genes (ADAMTS5, HES1, and MMP13), inhibition of cartilage matrix anabolic genes (COL2A1, ACAN, and SOX9) and the up-regulation of death genes (CASP4)." (PMID 32294904, 2020). "In addition, our finding that clodronate embedded in NPs may increase further SOX9 expression stimulates the search for new therapeutical strategies against osteoarthritis." (PMID 29236045, 2017). "In another study about osteoarthritis, it shows that the PARylation (poly (ADP-ribosyl)ation), which promotes the ubiquitination and degradation of SOX9, is modified by tankyrase." (PMID 39974732, 2025). "The analysis revealed a notable upregulation of key osteoarthritis markers, such as COL10A1, MMP13, and SPP1, along with downregulating chondrogenic markers, including ACAN, COL1A2, COL2A1, and SOX9." (PMID 39337501, 2024). "One group found that ADMA promoted SOX9 destabilization, which was mediated by DDAH1 in osteoarthritis." (PMID 37359559, 2023). "In conclusion, electroacupuncture for osteoarthritis is accomplished by upregulating the expression of HIF-1α, Sox9, and ACAN and downregulating the expression of MMP13 and ADAMTS5." (PMID 34760015, 2021). "This suggests that regulating SOX9 acetylation levels and SIRT1 activity could be a potential treatment strategy for osteoarthritis." (PMID 39974732, 2025). "Additionally, in osteoarthritis, there is an observed increase in the trimethylation of H3K9 and H3K27 and H3K9, 15, 18, 23, and 27 had less acetylation at the SOX9 promoters." (PMID 39974732, 2025). "The results demonstrated that miR-92a was downregulated in equine synovial fluid from horses with severe osteoarthritis and there was a significant increase in COMP, COL1A2, RUNX2 and SOX9 following miR-92a mimic treatment of equine chondrocytes in monolayer culture." (PMID 36555166, 2022).
osteoarthritis (continued). "Because TRPV4 also regulates the chondrogenic transcription factor SOX9, TRPV4 could indeed play a key role in osteoarthritis and the modulation of the chondrocyte phenotype." (PMID 29693628, 2018). "This study aimed to determine the collagen type II (COL2) and SOX9 expression in interleukin growth factor (IGF-1)-induced Wharton’s Jelly mesenchymal stem cells (WJMSCs) and the level of chondrogenic markers in co-culture IGF1-WJMSCs and IL1β-CHON002 as osteoarthritis (OA) cells model." (PMID 30140415, 2018). "In addition, the treatment with clodronate, a non-aminobisphosphonate used to manage osteoarthritis, did not affect the modulation of miR-204-5p, but it was able to upregulate SOX9 expression and prevent miR-204-5p downregulation induced by Il beta 1 treatment." (PMID 35216245, 2022).
gastric cancer (73 papers, 2011 to 2026). A primary or metastatic malignant neoplasm involving the stomach. "In gastric cancer, as the disease progresses, the methylation of the SOX9 promoter significantly increases, potentially causing SOX9 suppression in advanced stages." (PMID 39974732, 2025). "On the contrary, the analysis we performed in both the ACRG and the TCGA databases reinforced the worse prognosis associated with low SOX9 expression in gastric cancer." (PMID 31275454, 2019). "Several studies have reported high levels of SOX9 in gastric cancer, but the association with patient prognosis is poorly defined." (PMID 31275454, 2019). "A high expression level of SOX9 is associated with gastric cancers." (PMID 34879086, 2021). "The expression pattern of SOX9 in the normal human stomach, intestinal metaplasia, and gastric carcinoma have been reported, and the results indicated that SOX9 expression may be associated with gastric carcinogenesis and predict the risk of human intestinal gastric cancer." (PMID 29587675, 2018). "We found a negative correlation between high SOX9 expression and patient prognosis by analyzing data from GEPIA and the Xiantao Academic website and examining the correlation between SOX9 levels and the survival period of gastric cancer patients." (PMID 39523731, 2025). "In recent years, there has been growing recognition of the carcinogenic role of SOX9, with experimental studies identifying its potential cancer-promoting effects in various malignant tumors, including gastric cancer and lung adenocarcinoma." (PMID 40692865, 2025). "This investigation, conducted on a Turkish cohort of 150 patients with clinicopathological data, revealed moderate to strong SOX9 intensity in 85.3% of cases, with high SOX9 expression observed in 40% of gastric carcinoma cases." (PMID 39907598, 2025). "On the other hand, in gastric cancer, SOX9 promotes progression and metastasis in gastric cancers by the suppression of CD8+T cell responses." (PMID 38956258, 2024). "PLOD1 is upregulated in gastric cancer tissues and promotes tumorigenesis by activating the SOX9/PI3K/Akt/mTOR pathway." (PMID 39068670, 2024). "Exosomal circ0032821 regulated the proliferation, migration and invasion of oxaliplatin sensitive gastric cancer cells through the miR-515-5p/SOX9 axis, enhancing oxaliplatin resistance in gastric cancer cells." (PMID 39314750, 2024). "PLOD1 has been shown to promote cell growth and aerobic glycolysis by regulating the SOX9/PI3K/Akt/mTOR signaling pathway in gastric cancer." (PMID 37391802, 2023). "PPARδ collaborates with the hippo coactivator YAP1 to elevate the expression level of SOX9 and the progression of gastric cancer." (PMID 37183261, 2023). "It has been demonstrated that SOX9 enhances the epithelial-mesenchymal transitions in gastric cancer cells via the mechanism of activating the Hippo-YAP signaling pathways." (PMID 37183261, 2023). "In several human gastric cancer cell lines, SOX9 knockdown suppressed tumor growth by inhibiting Wnt/β-catenin signaling." (PMID 35864961, 2022). "Similar to our study, a prior study has also demonstrated SOX9 expression is common in gastric cancer." (PMID 35221802, 2022). "It has also been recently shown for cells of several types of cancer (glioma, pancreatic cancer, and stomach cancer) that the elevated expression of SOX9 leads to a decrease in CDKN1A and to the stimulation of cell division." (PMID 35884771, 2022). "As for molecular mechanisms, REG4 expression facilitated invasion and migration of gastric cancer cells by up-regulating SOX9 expression, in contrast to REG4 knockdown." (PMID 36172286, 2022). "SOX9 expression is elevated in human gastric cancer samples and correlated with poor clinical outcomes 53-55." (PMID 35864961, 2022). "We found frequent expression of SPOCK1 (in both nuclei and cytoplasm), MCL-1 and SOX9 in gastric cancer." (PMID 35221802, 2022).